WT1 (WT1 transcription factor)
Diseases named in the same sentence as WT1 in open-access papers (continued):
Sharing a sentence is not in itself a finding about the gene and the disease.
leukemia (continued). "Of those with active leukemia, 67% (6/9) were positive for BIRC5, 33% (3/9) for WT1, and 22% (2/9) for PRAME." (PMID 36248870, 2022). "It was reported that WT1 had a consistent up-regulation with CD34 in acute leukemia cells and also had a simultaneous down-regulation when leukemia cells were differentiated into mature cells." (PMID 36500358, 2022). "The capability of HAGE/WT1-ImmunoBody® induced T cells to recognise and kill HAGE and WT1 expressing leukaemia cells was then assessed using in vitro cytotoxicity assays." (PMID 34262856, 2021). "Recently, WT1 was shown to interact with TET2, and this interaction is critical for growth inhibition of leukemia cells." (PMID 33110919, 2020). "Comparable with the results reported about WT1 expression in MPN, its expression is also higher in leukemia cells and LSCs compared to normal healthy hematopoietic cells and is a possible prognostic factor to predict clinical outcome and to detect MRD." (PMID 32604862, 2020). "While WT1-specific CTLs and WT1-TCRs were identified many years ago, WT1-TCR gene-modified T cells eliminating leukemia cells were demonstrated in vitro and in vivo in a xenograft mouse model and leukemia-bearing NOD/SCID mice." (PMID 30622438, 2019). "WT1-TCR-CD4+T cells display helper activity for WT-1-specific CTL induction and cytotoxicity against leukemia cells." (PMID 30622438, 2019). "In mice, WT1 cooperates with the RUNX1/RUNX1T1 (AML1/ETO) fusion gene in the induction of acute leukemia, further emphasizing a role for WT1 in leukemia development." (PMID 29152069, 2017). "From these research databases, we selected four genes of interest, FLT-3, WT1, Bmi-1, and ABCG2, known as oncogenic and stem cell regulators that participate in leukemia initiation and progression." (PMID 26847520, 2016). "17AA(+)WT1 isoforms [17AA(+)KTS(+) and 17AA(+)KTS(-)] exert their anti-apoptotic function through stabilization of mitochondrial membrane in leukemia and solid tumors." (PMID 26090994, 2015). "qRT-PCR was performed on a wide range of leukemia and lymphoma cell lines to evaluate the transcription levels of the WT1, AWT1 and the non-coding antisense transcript WT1-AS." (PMID 24405639, 2014). "Immunologic, clinical, and/or molecular responses have been observed in adults with leukemia treated with peptide vaccines targeting PR1, WT1, and the bcr/abl breakpoint peptide." (PMID 23847759, 2013). "A phase 1 study of gamma retrovirally modified T cells to treat relapsed leukaemia has recently been initiated to investigate the safety and efficacy of a recombinant αβ TCR specific for HLA-A2/WT1 peptide antigen (ClinicalTrials.gov; NCT01621724)." (PMID 23840834, 2013). "Compared with Wilm’s tumor (WT1) gene, PRAME gene, as another widely expressed leukemia gene, is more widely expressed in patients with normal karyotypes." (PMID 23691459, 2012). "A number of groups are investigating the use of T cells specific to the leukemia antigens such as Wilms tumor 1 (WT1) and proteinase 3 (PR3) to prevent or treat leukemia relapse following HSCT." (PMID 21740581, 2011). "Thus, the reduction of WT1 and induction of SGK1 levels appear to be a common phenomenon during differentiation in the hematopoietic and leukemia models." (PMID 40613901, 2025). "Consequently, the overexpression of the WT1 gene has been used as a biological marker for diagnosing and evaluating minimal residual disease (MRD) in leukemia." (PMID 40022126, 2025). "Furthermore, these WT1-CTLs effectively killed AML cells with a CD34+/CD38− immunophenotype, a cell compartment which is classically enriched with leukemia-initiating cells [(LICs) or leukemic stem cells (LSCs)]." (PMID 39711535, 2024).
leukemia (continued). "In fact, a high-avidity TCR, S117A-TCR-transduced CD4+ T cells had a higher frequency of granzyme B/perforin-double positive cells and showed more potent cytotoxicity against WT1-expressing and HLA-DPB1*05:01-positive leukemia cells, compared to wt-TCR-transduced CD4+ T cells." (PMID 36939853, 2023). "In a cohort of 59 leukemia/lymphoma cell lines, we showed aberrant expression for WT1 mRNA, which does not always translate into protein levels." (PMID 37444601, 2023). "On the other hand, they lysed neither WT1332 peptide-non-pulsed B-LCL nor HLA-DPB1*05:01-negative WT1-expressing leukemia cell line, K562." (PMID 36939853, 2023). "Similarly, WT1-specific CD8 T cells were found to be induced in azacitadine and donor lymphocyte infusion treatment contributing to graft versus leukemia effect in MDS and AML patients." (PMID 37928542, 2023). "Interestingly, in these 3 patients, the pattern of CMV-CTL apparently changed inversely to that of WT1-CTL, and high expression of TIM-3 and PD-1 on CMV-CTL or WT1-CTL seemed to correlate with positive MRD and later leukemia relapse in two of them." (PMID 36824620, 2022). "Besides, vorinostat and bortezomib have been reported to significantly inhibit WT1 gene expression in MO7-e and P39 cell lines, which are in vitro models for leukemia and MDS, respectively." (PMID 35465313, 2022). "Indeed, WT1 repressed SRPK1 transcription in a non‐tumoral Denys Drash Syndrome podocyte cell line, whereas a more recent study reported that WT1 acts as a transcriptional activator of SRPK1 in prostate cancer and leukaemia cells." (PMID 34092037, 2021). "The WT1 gene is highly expressed in human leukemia cells, and not only plays an important role in the proliferation and differentiation of leukemia cells but is also associated with the occurrence, development, and prognosis of leukemia." (PMID 33659248, 2021). "Wilms’ tumor 1 (WT1), a zinc-finger transcription factor and an epigenetic modifier, has been proposed as prognostic marker of several solid and hematologic tumors because is frequently overexpressed in leukemias, lung, colon, or pancreatic cancers." (PMID 33917307, 2021). "The WT1 gene is highly expressed in various types of leukemias including acute myeloblastic leukemia (AML), acute lymphoblastic leukemia (ALL), and chronic myelocytic leukemia (CML) and is important for leukemia treatments, progression, and prognosis." (PMID 32178481, 2020). "HLA-DPB1*05:01-WT1332-TCR-modified-CD4+ T cells displayed a strong proliferative response and Th1-type cytokine production in response to WT1332 peptide, WT1 protein, or WT1-expressing tumor cell lysate and lysed HLA-DPB1*05:01+ WT1+ human leukemia cells via the granzyme B/perforin pathway." (PMID 30622438, 2019). "The Flt3/ITD and Wt1 mutations did not consistently cooperate to recapitulate human AML in our model; thus, a third hit is likely necessary to transform fully to leukemia." (PMID 30450160, 2018). "WT1 peptide vaccine with Montanide as an adjuvant induces detectable WT1-specific CD8+ T cell responses with clonal TCR enrichment, which may be capable of controlling leukemia recurrence in the setting of minimal residual disease." (PMID 29344432, 2018). "For example, WT1 is not a leukemia-specific molecule, being detected at low levels in various normal tissues, such as gonads, kidney and the hematopoietic system, but is highly over-expressed by leukemia cells." (PMID 29466292, 2018). "Given that not all leukemias express WT1, a better understanding of how WT1 expression is regulated is critical to the development of WT1-based immunotherapies." (PMID 25794157, 2015). "Using quantitative real time PCR and immunohistochemistry, presented data showed that WT1 is not only highly expressed in leukaemia but also in a variety of nonhaematopoetic malignancies including lung cancer, colon cancer and pancreatic carcinomas." (PMID 27275197, 2015).
leukemia (continued). "It has been reported that the Wilms’ Tumor Gene (WT1) is expressed in leukemia blasts, irrespective of the subtypes of acute leukemia." (PMID 19662212, 2007). "Colony formation by normal bone marrow cells of HLA-A2-positive patients were not inhibited by the WT1 leukemia-specific CTL." (PMID 19662212, 2007). "Additionally, the co-incubated T-cells showed a robust cytotoxic activity lysing WT1-overexpressing THP-1 leukemia cells while sparing WT1-negative hematopoietic cells in vitro." (PMID 39697225, 2024). "In one patient, the BRAF mutation was lost during relapse, while the rest of RAS-related genes (KRAS and WT1), and the KMT2A::MLLT3 fusion persisted (Case No. 2), suggesting that the BRAF mutation may not be the driver mutation for this leukemia." (PMID 38791222, 2024). "Indeed, WT1 expression can be used in patients for MRD assessment and follow-up posttreatment when no other marker is available and also represents a valuable leukemia-associated antigen." (PMID 35486629, 2022). "We established two new immune-competent mouse models of leukemia persistence (expressing or not expressing Wt1) that are useful to study the role of the immune response in the control of residual AML cell proliferation and survival and test new immunotherapeutic approaches." (PMID 35486629, 2022). "Since WT-1 gene expression was not the specific marker for leukemia or MDS in patients, we speculated that a target gene panel for MRD would be more accurate." (PMID 34422653, 2021). "On the other hand, WT1 was not a specific molecular marker of leukemia." (PMID 33214615, 2020). "Despite its ubiquitous expression during embryogenesis, WT1 expression in normal individuals is limited to renal podocytes, gonadal cells, and CD34+ bone marrow cells, where expression is significantly lower than in leukaemia cells (10–100 fold), making it an excellent target for immunotherapy." (PMID 30678059, 2019). "The high level WT1 specific CD8+ T cell at the time of WT1 PCR relapse might help to control the leukemia, since the patient did not have morphologic relapse until 18 months after the last WT1 vaccination." (PMID 29344432, 2018). "None of the knock-in Wt1+/R394W mice developed overt leukemia." (PMID 30450160, 2018). "Furthermore, higher levels of wild-type WT1 have been found in most cases of leukemia, compared with normal bone marrow (BM) or peripheral blood (PB)." (PMID 28477011, 2017). "However, despite numerous clinical studies providing solid evidence for the role of high WT1 levels in leukaemia, its role is not yet clearly defined in the context of other known risk factors relevant for AML prognosis." (PMID 26597595, 2016). "In addition, transcriptional initiation from an alternative promoter located in intron 1 results in the production of a smaller N-terminal truncated WT1 protein (AWT1 also known as sWT1) and the N-terminal truncated WT1 has more oncogenic potential than wild-type WT1 in leukemia cells." (PMID 26090994, 2015). "WT1 expression in progenitor cells is minimal or absent, and the limited WT1 tissue expression in adults suggests that WT1 may be a therapeutic leukemia target." (PMID 23394714, 2013). "WT1 expression in progenitor cells is minimal or absent, and the limited WT1 tissue expression in adults suggests that WT1 may be a leukemia therapy target." (PMID 23241263, 2012). "We developed a novel, oral, helper epitope-containing WT1 protein vaccine (B. longum 2656) to examine whether or not B. longum 420/2656 combination further accelerates the CD4+ T cell help-enhanced antitumor activity in a model of murine leukemia." (PMID 36803483, 2023). "Hence, modulation of intercellular redox homeostasis and downregulation of WT1 expression both are associated with differentiation of HL-60 leukemia cells, and SHK may be an agent for leukemia differentiation therapy under non-cytotoxic concentration." (PMID 38026987, 2023).
leukemia (continued). "Thus, it was unavoidable that some patients may receive IFN-α treatment based on elevated WT1 which was not relative to leukemia in fact." (PMID 33740924, 2021). "For instance, though WT1 is expressed in normal tissues such as gonads, kidney and normal hematopoietic cells, it has been used in clinical trials for targeted immunotherapy especially peptide-based vaccine for leukemia without any serious immunologic adverse events being observed." (PMID 31575892, 2019). "In a transgenic mice model, co-expression of WT1 and the AML-ETO fusion protein led to a rapid onset of murine leukemia; however, neither WT1 nor AML-ETO alone sufficed here." (PMID 37444601, 2023). "Of the 19 patients with active disease, including those leukemias without elevated TAA/ABL1, the blood levels of WT1/ABL1, PRAME/ABL1, and BIRC5/ABL1 exceeded healthy donors (p<0.0001, p=0.0286, and p=0.0064 respectively)." (PMID 36248870, 2022). "ddPCR simultaneously quantitated mRNA expression of WT1, PRAME, BIRC5, and ABL1 and the TAA/ABL1 blood ratio was measured in patients with and without active leukemia after HCT." (PMID 36248870, 2022). "Although the pathogenesis of WT1 in leukemia has not been completely revealed, the phenomenon that low expression of WT1 and high expression of WT1 are accompanied with clinical remission and relapse respectively shows that WT1 may be a potential prognostic factor in acute leukemia." (PMID 26992216, 2016). "Because WT1 was not a leukemia-specific molecular marker, a relatively higher cut-off value could spare pediatric AML patients who had slightly elevated WT1 levels but were actually in molecular remission from further interventions." (PMID 33740924, 2021). "Because of limited availability of patient material, we did not study immunity to other known CML antigens such as WT1 or the BCR-ABL fusion region peptides, but we would expect that CTL immunity against these and perhaps other leukemia antigens should be similarly increased." (PMID 20668669, 2010). "The results from current study have demonstrated that the WT1 gene was “universally” expressed at diagnosis in a small cohort of local adult patients (18/18) with acute leukemia, including both AML and ALL, regardless of lineages of the leukemia cell origin." (PMID 19662212, 2007). "We demonstrated that CMV- specific T cell clones were able to repsond to a leukemia antigen stimulus, WT1, but whether or not CMV infection could affect the leukemia-specific T cells, and whether CMV-specific T cells are able to cross-react against leukemia cells remain to be explored." (PMID 36824620, 2022). "In the same study, infused allogeneic donor WT1-specific CTLs exerted an antileukemia effect without exacerbating GVHD, and those CTLs pre-cultured with a rhIL-21 expressing memory T-cell phenotype achieved a notably durable leukemia remission for longer than 30 months." (PMID 25517545, 2014).
acute myeloid leukemia (152 papers, 2006 to 2026). Acute myeloid leukemia (AML) is a group of neoplasms arising from precursor cells committed to the myeloid cell-line differentiation. "A Phase 2 study investigated the effects of vaccinating 30 patients with Acute Myeloid Leukemia and at very high risk of relapse, using DCs electroporated with Wilms’ tumor 1 (WT1) mRNA as a post-remission treatment." (PMID 39311156, 2024). "Mutations in exons 7 and 9 of WT1 have been identified in acute myeloid leukemia and are related to poorer prognosis and resistance to treatment." (PMID 35495123, 2022). "The prognostic impact of Wilms tumor 1 (WT1) mutations remains controversial for patients with acute myeloid leukemia (AML)." (PMID 33968731, 2021). "In an early phase II clinical trial, acute myeloid leukemia patients were vaccinated by intradermal injection with autologous DC electroporated in vitro with mRNA, encoding Wilms ́ tumor 1 (WT1) antigen in bi-weekly intervals for four cycles." (PMID 32917034, 2020). "WT1 gene encodes a transcription factor WT1, which is overexpressed in a wide variety of tumor types, including acute myeloid leukemia (AML)." (PMID 28789687, 2017). "Previously, we found that most patients with acute myeloid leukemia (AML) expressed at least one of the leukemic associated antigens (LAAs) WT1, survivin and TERT, and different combinations of the three LAAs predicted negative clinical outcomes." (PMID 28477011, 2017). "In acute leukemia, WT1 mutations have been reported in 10% of patients with acute myeloid leukemia (AML)." (PMID 27275197, 2015). "Here we address loss or mutation of WT1 as a potential immune evasion mechanism in patients from a clinical phase II trial of WT1 peptide vaccination in acute myeloid leukaemia (AML)." (PMID 20092642, 2010). "Furthermore, the elevated expression of WT1 protein is associated with poor prognosis and worse long-term outcomes in acute myeloid leukemia (AML), often leading to relapse." (PMID 40022126, 2025). "Moreover, mutations in WT1 have been recurrently identified in acute myeloid leukemia and associated with poor prognosis and chemotherapy resistance." (PMID 33632303, 2021). "Furthermore, several independent studies have proposed WBP5, and its association with Wilms Tumor-1 (WT1) expression, as part of a gene expression-based risk score for predicting survival and clinical outcome in patients with Acute Myeloid Leukaemia (AML)." (PMID 32103106, 2020). "The Wilms’ tumor gene 1 (WT1) is recurrently mutated in acute myeloid leukemia." (PMID 29152069, 2017). "CV-501 is a different HLA class II restricted peptide vaccine based on WT1, which has been studied in patients with acute myeloid leukemia (AML)." (PMID 40129984, 2025). "aAVC therapy is a cellular therapy platform, and we demonstrated that many types of antigens were used, such as OVA, MART-1, NY-ESO-1, and WT1 antigens in murine models and also against human relapsed and refractory acute myelogenous leukemia patients." (PMID 38361934, 2024). "Wilms' tumor gene 1 (WT1) mRNA quantification is a useful marker of measurable residual disease in acute myeloid leukemia (AML)." (PMID 38334897, 2024). "Apart from FLT3, there are some other recurrent genetic alterations that are also found in other acute myeloid leukemia subtypes, including WT1 (14%), NRAS (10%), KRAS (4%) and MYC amplification (12%)." (PMID 38921185, 2024). "The first TCRm T-cell engaging bispecific Ab RO7283420 has been evaluated in acute myeloid leukemia (AML) targeting HLA-A2/WT1." (PMID 39594730, 2024). "This, in addition to the identification of WT1 as a predictor of acute myeloid leukemia relapse and the fact that its overexpression is related to poor prognosis, has led to the consideration of WT1 as an oncogene." (PMID 39768169, 2024). "A 2012 trial (NCT01640301) attempted to treat acute myeloid leukemia with WT1 high-affinity CD8+ T cells, but the trial is currently closed for enrollment, and the results have not been reported." (PMID 37649123, 2023).